RPA1 (replication protein A1)
Description:
As part of the heterotrimeric replication protein A complex (RPA/RP-A), binds and stabilizes single-stranded DNA intermediates that form during DNA replication or upon DNA stress. It prevents their reannealing and in parallel, recruits and activates different proteins and complexes involved in DNA metabolism. Thereby, it plays an essential role both in DNA replication and the cellular response to DNA damage. In the cellular response to DNA damage, the RPA complex controls DNA repair and DNA damage checkpoint activation. Through recruitment of ATRIP activates the ATR kinase a master regulator of the DNA damage response. It is required for the recruitment of the DNA double-strand break repair factors RAD51 and RAD52 to chromatin in response to DNA damage. Also recruits to sites of DNA damage proteins like XPA and XPG that are involved in nucleotide excision repair and is required for this mechanism of DNA repair. Also plays a role in base excision repair (BER) probably through interaction with UNG. Also recruits SMARCAL1/HARP, which is involved in replication fork restart, to sites of DNA damage. Plays a role in telomere maintenance. As part of the alternative replication protein A complex, aRPA, binds single-stranded DNA and probably plays a role in DNA repair. Compared to the RPA2-containing, canonical RPA complex, may not support chromosomal DNA replication and cell cycle progression through S-phase. The aRPA may not promote efficient priming by DNA polymerase alpha but could support DNA synthesis by polymerase delta in presence of PCNA and replication factor C (RFC), the dual incision/excision reaction of nucleotide excision repair and RAD51-dependent strand exchange. RPA stimulates 5'-3' helicase activity of the BRIP1/FANCJ.
Synonyms: REPA1; RPA70; HSSB; RF-A; RP-A; MST075; PFBMFT6
Tractability: Small molecule: a structure with a bound ligand is known; a high-quality ligand is known; it has a binding pocket of medium quality. PROTAC: UniProt records ubiquitination sites on it; ubiquitination databases record sites on it; its protein half-life has been measured; a small molecule that binds it is known.
Gene: Protein-coding gene on chromosome 17 (1,829,702 to 1,900,082, forward strand). Ensembl gene ENSG00000132383.
Subcellular location: Nucleus; Nucleus, PML body
Subcellular location (Human Protein Atlas): Nucleoplasm
Pathways (Reactome):
DNA Repair: Dual Incision in GG-NER; Dual incision in TC-NER; Fanconi Anemia Pathway; Formation of Incision Complex in GG-NER; Gap-filling DNA repair synthesis and ligation in GG-NER; Gap-filling DNA repair synthesis and ligation in TC-NER; HDR through Homologous Recombination (HRR); HDR through Single Strand Annealing (SSA); PCNA-Dependent Long Patch Base Excision Repair; Presynaptic phase of homologous DNA pairing and strand exchange; Processing of DNA double-strand break ends; Recognition of DNA damage by PCNA-containing replication complex; Termination of translesion DNA synthesis; Translesion Synthesis by POLH; Translesion synthesis by POLI; Translesion synthesis by POLK; Translesion synthesis by REV1
Cell Cycle: Activation of ATR in response to replication stress; G2/M DNA damage checkpoint; Removal of the Flap Intermediate from the C-strand
Cellular responses to stimuli: HSF1 activation; Regulation of HSF1-mediated heat shock response
DNA Replication: Activation of the pre-replicative complex; Removal of the Flap Intermediate
Disease: Impaired BRCA2 binding to RAD51
Metabolism of proteins: SUMOylation of DNA damage response and repair proteins
Reproduction: Meiotic recombination
Gene Ontology:
Molecular function: chromatin-protein adaptor activity; damaged DNA binding; G-rich strand telomeric DNA binding; protein binding; single-stranded DNA binding; single-stranded telomeric DNA binding; chromatin binding; DNA binding; nucleic acid binding
Biological process: base-excision repair; DNA damage response; DNA repair; DNA replication; double-strand break repair via homologous recombination; mismatch repair; nucleotide-excision repair; protein localization to chromosome; protein localization to site of double-strand break; telomere maintenance; DNA recombination; DNA-templated DNA replication; telomere maintenance via telomerase; chromatin organization
Cellular component: chromosome, telomeric region; DNA replication factor A complex; nucleoplasm; nucleus; PML body; site of DNA damage; site of double-strand break; condensed chromosome; condensed nuclear chromosome; lateral element; male germ cell nucleus; nuclear chromosome
Genetic constraint (gnomAD): Loss-of-function variants: 46 observed, 71.94 expected, observed/expected ratio (o/e) 0.64, 90% interval 0.5 to 0.82. The upper end of that interval is the gene's LOEUF score, 0.82, which puts it in group 3 of 6, group 1 being the genes least tolerant of losing a copy. Missense variants: 655 observed, 744.47 expected, observed/expected ratio (o/e) 0.88, 90% interval 0.82 to 0.94. Synonymous variants: 260 observed, 271.6 expected, observed/expected ratio (o/e) 0.96, 90% interval 0.86 to 1.06.
Gene-disease validity (ClinGen):
ClinGen rates the evidence that RPA1 causes each of these diseases.
dyskeratosis congenita and related telomere biology disorder (autosomal dominant): Limited. A dyskeratosis congenita caused by impaired telomere maintenance resulting in short or very short telomeres.
Homologues: Orthologues: chimpanzee RPA1 (99% identical), macaque RPA1 (97% identical), guinea pig RPA1 (89% identical), rabbit RPA1 (89% identical), dog RPA1 (88% identical), pig RPA1 (87% identical), rat Rpa1 (86% identical), mouse Rpa1 (86% identical), tropical clawed frog rpa1 (73% identical), zebrafish rpa1 (63% identical), Drosophila melanogaster RPA1 (43% identical), Caenorhabditis elegans rpa-1 (27% identical), and 2 more.
Diseases named in the same sentence as RPA1 in open-access papers:
RPA1 is named in the same sentence as 128 diseases in open-access papers, as found by Europe PMC text mining. Sharing a sentence is not in itself a finding about the gene and the disease. The quoted sentences say what the papers report.
breast carcinoma (10 papers, 2013 to 2026). "In luminal A, ER + breast cancers, low RPA1 was associated with poor BCSS (P = 0.007) and DMFS (P = 0.007)." (PMID 36997566, 2023). "In ER + breast cancers that received endocrine therapy, low RPA1, 2 or 3 was associated with poor BCSS and DMSF." (PMID 36997566, 2023). "In Luminal A breast cancers, low RPA1 was associated with shorter BCSS (P = 0.006) and DMFS (P = 0.021)." (PMID 36997566, 2023). "In the whole cohort, low RPA1 was associated with poor outcome in terms of shorter breast cancer-specific survival (BCSS) (P < 0.0001) and distant metastasis-free survival (DMFS) (P < 0.0001)." (PMID 36997566, 2023). "In ER + breast cancer patients who received endocrine therapy, low RPA1 was associated with shorter BCSS (P < 0.0001) and DMFS (P < 0.0001) suggesting that low RPA expression may predict limited response to endocrine therapy." (PMID 36997566, 2023). "KILR overexpression elicited apoptosis specifically in breast cancer cells, mediated by the binding and sequestration of RPA1 in nuclear foci." (PMID 38745269, 2024). "Reduced KILR expression promotes breast cancer cell proliferation by increasing the available pool of RPA1 and speed of DNA replication." (PMID 38745269, 2024). "Breast cancer cells partially depleted of RPA1 by siRNA treatment also become over-sensitive to DNA damage." (PMID 38745269, 2024). "These genes were markedly differentially expressed in breast cancer tissues compared to normal tissues except for RPA1 and RPA2." (PMID 36533385, 2023). "Immunohistochemically, we observed that RPA1 protein was expressed only in the nucleus in both normal and breast cancer tissue." (PMID 36997566, 2023). "Of note, the BORG lncRNA has been shown to physically interact with RPA1 in breast cancer, suggesting KILR may interact with RPA1 via the BORG-like motifs in its sequence." (PMID 38745269, 2024). "The data suggested that RPA1 downregulation may be an early event during breast cancer pathogenesis." (PMID 36997566, 2023). "Taken together, these results suggest that by reducing the pool of available RPA1, overexpression of KILR in breast cancer cells mimics the phenotype of RPA1 knockdown." (PMID 38745269, 2024).
esophageal cancer (10 papers, 2017 to 2025). A primary or metastatic malignant neoplasm involving the esophagus. "Di and colleagues (2014) demonstrated that RPA1 or RPA2 silencing increased the radiosensitivity of radioresistant esophageal cancer cells." (PMID 38137049, 2023). "The sensitivity of radiation‐resistant esophageal cancer cells to radiation can be enhanced by inhibiting RPA1 or RPA2 expression." (PMID 34766149, 2021). "Previous studies have shown that RPA1 is upregulated in colon cancer and esophageal carcinoma; moreover, it is related to the extent of illness." (PMID 32552682, 2020). "Furthermore, miRNA-based biomarkers (e.g., miR-132-3p, miR-576-5p) correlate with radiosensitivity in esophageal cancer; glioblastoma genes like POLQ, PRIM1, and RPA1 are linked to radioresistance, while miR-153-3p overexpression enhances radiosensitivity." (PMID 40277781, 2025). "Inhibiting RPA1 appears to increase the radiosensitivity of esophageal cancer cells." (PMID 39125953, 2024). "Overexpression RPA1 was related to poor clinical outcomes in bladder cancer and esophageal cancer." (PMID 36277983, 2022). "RPA1 expression was shown to be increased and correlated with the severity of colon cancer and esophageal carcinoma, suggesting that RPA1 could be used as prognostic indicators or as targets for treatments." (PMID 36277983, 2022). "Although an increased resistance to ionizing radiation was demonstrated in the TE-1R cell line with overexpression of RPA1, since the cell line was generated from irradiated esophageal carcinoma TE-1 cells the radioresistance cannot be conclusively attributed to RPA1 overexpression." (PMID 32849834, 2020). "High RPA1 expression may serve as a marker of poor prognosis in colon cancer, esophageal carcinoma or hepatocellular carcinoma patients." (PMID 32849834, 2020). "Accordingly, high RPA1 and RPA2 expression levels reportedly increased radioresistance in oesophageal cancer 18 and predicted a poor prognosis in oesophageal cancer 19, colon cancer 20, astrocytic tumours 21 and bladder urothelial cancer." (PMID 28557284, 2017).
lymphoma (9 papers, 2014 to 2023). A malignant (clonal) proliferation of B- lymphocytes or T- lymphocytes which involves the lymph nodes, bone marrow and/or extranodal sites. "Among lymphomas, we observed 4 Hodgkin’s lymphoma (n = 1 novel, n = 1 ultra-rare) and 3 non-Hodgkin’s lymphoma (n = 1 novel, n = 1 ultra-rare) with RPA1 variants." (PMID 37869077, 2023). "From patients with hematologic malignancies, RPA1 variants were most common in B-ALL (n = 13), followed by lymphoma (n = 7), AML (n = 5), and T-ALL (n = 4)." (PMID 37869077, 2023). "Stably expressed tRF‐CU1276 suppresses a DNA dynamics regulator (RPA1), thereby regulating damage responses to molecular and suppressing lymphoma cell proliferation." (PMID 35957621, 2022). "Stable expression of CU1276 in Burkitt lymphoma cells can inhibit cell proliferation, and when exogenous RPA1 is coexpressed, the proliferation of lymphoma cells can be restored." (PMID 34537813, 2021). "Stable expression of tRF-CU1276 can inhibit a DNA dynamics regulator, endogenous RPA1, thus regulating the molecular DNA damage response and inhibiting proliferation in lymphoma cell lines." (PMID 33665159, 2020). "Nevertheless, control shRNAs targeting essential genes (Rpa1, Rpa3 and Polr2b;) were consistently depleted in all four replicates, as were shRNAs targeting genes that either cooperated with Myc (Prmt5 and Odc) or belonged to known oncogenic pathways in Eμ-myc lymphomas (Adsl and Rsl24d1)." (PMID 27635472, 2016). "Positive AGO pulldown of CU1276 indicated RISC incorporation and putative binding on 3’-UTR of Replication Protein A1 (RPA1), which provided the molecular basis of CU1276-mediated repression of the molecular response to DNA damage in lymphomas." (PMID 33353171, 2020). "Furthermore, the expression of CU1276 in a lymphoma cell line could inhibit cell proliferation and regulate the molecular response to DNA damage due to inhibition of endogenous replication protein A1 (RPA1), which is involved in many important aspects of DNA dynamics." (PMID 32887641, 2020).
anthrax (8 papers, 2010 to 2022). "Results obtained in the current research enable the claim that modified anthrax antigens rPA1+2, rPA3+4 and rPA83m are resistant to degradation during extended storage under various temperature conditions and can serve as the basis for an anthrax vaccine." (PMID 35456639, 2022). "Considering previously proven adjuvant properties and safety of SPs, their compositions with rPA83m/rPA1+2/rPA3+4 in any combinations might be suitable as a basis for new-generation anthrax vaccines." (PMID 35456639, 2022). "Thus, we consider the compositions of SPs with any one of modified anthrax antigen or with the combination of rPA1+2 and rPA3+4 as prospective anthrax vaccine candidates that are worthy of further study." (PMID 35456639, 2022).
glioblastoma (8 papers, 2011 to 2026). The most malignant astrocytic tumor (WHO grade IV). "To demonstrate that this cellular phenotype was specifically associated with RPA1 over-expression, we constructed a conditional, isopropyl β-D-1-thiogalactopyranoside (IPTG)-inducible-RPA1 model system in the human glioblastoma line T98G based on the pTUNE vector (Origene)." (PMID 21901111, 2011).
lung carcinoma (8 papers, 2017 to 2025). "Above all, in DNA repair polymorphisms, there was a significant association between EXO1 rs1776148, rs1047840, RPA1 rs5030740, and prognosis in lung cancer." (PMID 36277983, 2022). "In this study, we focus on evaluating association between DNA repair polymorphisms of EXO1, RPA1, and prognosis in lung cancer patients whom received platinum-based chemotherapy." (PMID 36277983, 2022). "Our results indicated that EXO1 rs1776148, rs1047840, and RPA1 rs5030740 were significantly associated with prognosis of lung cancer." (PMID 36277983, 2022). "In this study, we evaluated whether polymorphisms in DNA damage and repair genes (EXO1, RPA1, PMS1, and PMS2) were associated with prognosis and response to platinum-based chemotherapy in lung cancer patients." (PMID 36277983, 2022). "The genotypes of RPA1 rs5030740, EXO1 rs1776148, and rs1047840 may be a biomarker contribute to predict the prognosis of platinum-based chemotherapy lung cancer patients." (PMID 36277983, 2022).
nasopharyngeal carcinoma (8 papers, 2017 to 2024). A carcinoma arising from the nasopharyngeal epithelium. "Among the single cases of solid tumors (germ cell tumor, melanoma, nasopharyngeal carcinoma, and papillary thyroid carcinoma), 2 ultra-rare and 1 novel RPA1 variants were found." (PMID 37869077, 2023). "This study reveals a functional germline polymorphism at RPA1 to be associated with survival outcome of patients with nasopharyngeal carcinoma (NPC)." (PMID 32440486, 2020). "A similar study in a nasopharyngeal carcinoma (NPC) (CNE2RR) cell line induced the expression of NFBD1, BRCA1, BRCA2, RPA1, and RAD51 proteins widely associated with HR and radioresistance." (PMID 34900673, 2021). "However, it has also been reported that an increase in the gene expression level of DDR genes may lead to resistance to cisplatin chemotherapy, while the overexpression of BRCA1, BRCA2, RAD51 and RPA1 has been observed in hypopharyngeal and nasopharyngeal carcinoma cells resistant to radiotherapy." (PMID 37740039, 2023). "Moreover, western blotting unveiled that circCDYL2 promoted the expression levels of RAD51 protein in nasopharyngeal carcinoma cells, while it did not influence the expression of BRCA1, RPA1, or Ku70, a key protein within the NHEJ pathway." (PMID 38654320, 2024).
ovarian carcinoma (8 papers, 2018 to 2026). A malignant neoplasm originating from the surface ovarian epithelium. "Furthermore, the alteration in the gene RPA1, integral to DNA repair machineries, has been correlated with breast and ovarian cancers." (PMID 37314494, 2023). "We have previously shown that FEN1 17, RPA1 (manuscript under preparation) and XRCC1 18 are key predictor of platinum resistance in ovarian cancers." (PMID 34373746, 2021).
colon cancer (7 papers, 2017 to 2025). "Our data encourage further studies to explore the possibility of using circulating RPA1 in monitoring treatment response in BRAFV600E- mutated colon cancer." (PMID 37106808, 2023). "Since RPA1 has been shown to act as an oncogene during colorectal cancer development, it could potentially serve as diagnostic indicator for colon cancer." (PMID 37106808, 2023). "Altogether, these results indicate a potential oncogenic role of RPA1 in BRAFV600E-mutated colon cancer and suggest that upregulation of RPA1 expression is a molecular feature of BRAFV600E-mutated colon cancer that could be associated with the development of vemurafenib-resistant phenotype." (PMID 37106808, 2023). "Proteomic expression profile analysis by UALCAN based on tumor histology using data on colon cancer from the CPTAC dataset revealed that only RPA1 protein expression was significantly increased in mucinous vs. non-mucinous colon cancer." (PMID 37106808, 2023). "Altogether, these findings posit that RPA1 could serve as a novel target for chemosensitization in colon cancer." (PMID 37106808, 2023). "Recent studies have shown that elevated expression of MCM3 in tumor tissues of hepatocellular carcinoma patients predicted worse overall survival, while RPA1 being demonstrated as a candidate oncogene which influences tumor biological behaviors in many cancers including colon cancer." (PMID 31581454, 2019). "Importantly, RPA1 knockdown potentiated the anti-proliferative effect of oxaliplatin in colon cancer cells, which could be ascribed to inhibition of DNA synthesis evidenced by reduced number of cells in the S phase." (PMID 37106808, 2023). "Thus, upregulation of secreted RPA1 protein could represent an important prognostic factor and a potential novel target for chemosensitization in BRAFV600E-mutated colon cancer." (PMID 37106808, 2023). "Similarly, it was previously reported that RPA1 protein may be used as a prognostic factor in colon cancer patients where increased expression of RPA1 protein was significantly associated with shorter overall survival." (PMID 37106808, 2023). "Further studies are required to investigate the potential of RPA1 and HSPA5/GRP78 in the real-world setting using clinical samples and to examine their roles in determining cancer cell response to BRAFV600E inhibition, not only in colon cancer but also in other BRAFV600E-mutated cancers." (PMID 37106808, 2023). "Increased level of RPA1 and reduced level of HSPA5/GRP78 were the most prominent secretory features of vemurafenib-resistant colon cancer cells, which were also specifically correlated with BRAFV600E genotype and poor survival outcomes in colon cancer patients with BRAFV600E mutation." (PMID 37106808, 2023). "Indeed, RPA1 has been previously shown to promote proliferation of colon cancer cells, since knockdown of RPA1 substantially decreased the rate of cell proliferation, whereas overexpression of RPA1 substantially raised the cell proliferation rate of colon cancer cells." (PMID 37106808, 2023). "In this context, targeting RPA1 may represent a novel and promising strategy to overcome resistance to BRAFV600E inhibition in colon cancer." (PMID 37106808, 2023).